DUX4L6 (double homeobox 4 like 6 (pseudogene))
Description:
May be involved in transcriptional regulation.
Gene: Unprocessed pseudogene on chromosome 4 (190,074,525 to 190,075,799, forward strand). Ensembl gene ENSG00000281058.
Subcellular location: Nucleus